JAK3 (Janus kinase 3)
Diseases named in the same sentence as JAK3 in open-access papers (continued):
Sharing a sentence is not in itself a finding about the gene and the disease.
Obesity (10 papers, 2013 to 2025). Accumulation of substantial excess body fat. "In humans, the mechanism behind tofacitinib-induced weight gain has been reported to be linked to a reduction in JAK3 activity, which is implicated in obesity pathogenesis." (PMID 40045302, 2025). "Since meta-analyses show cognitive impairment as co-morbidity of obesity, the present study demonstrates the mechanistic role of Jak3 in obesity associated cognitive impairment." (PMID 36145091, 2022). "Intestinal deficiency of Jak3 leads to increased microglial activation in the brain during HFD-induced obesity." (PMID 36145091, 2022). "HFD is a known cause of human obesity, and our previous report suggested decreased colonic mucosal expression of Jak3 during human obesity." (PMID 36145091, 2022). "Previously, we reported that colonic mucosal Jak3 is decreased in human obese condition, and a deficiency of Jak3 expression in mice leads to exaggerated symptoms of obesity." (PMID 36145091, 2022). "Previously, we reported that Jak3 regulated intestinal inflammation and predisposition to obesity-associated metabolic syndrome through the regulation of TLR-mediated mucosal tolerance." (PMID 36145091, 2022). "As our previous report suggested that global Jak3 deficiency leads to obesity-associated metabolic syndrome, this study demonstrated that global Jak3 deficiency in mice also leads to colonic dysbiosis." (PMID 36145091, 2022). "High-fat diet reduces the intestinal expression of Jak3, and an in vivo reconstitution of these conditions in mice leads to colonic dysbiosis and obesity-associated AD pathology." (PMID 36145091, 2022). "Since our previous report suggested that global Jak3 deficiency in mice leads to obesity-associated type 2 diabetes, in this study, we showed the same global Jak3 deficiency also causes gut-dysbiosis-associated cognitive impairment." (PMID 36145091, 2022). "The triggering receptors on microglial cells 2 (TREM2) interact with Jak3 in the brain, and IEC deficiency of Jak3 leads to an impairment of Jak3 interactions with TREM2 in the brain during HFD-induced obesity." (PMID 36145091, 2022). "Previously, we reported that obese humans have a reduced expression of intestinal Jak3 46, and a chronic reconstitution of these conditions in our novel mouse model led to obesity-associated metabolic syndrome." (PMID 36145091, 2022). "Intestinal epithelial cell (IEC)-specific deficiency of Jak3 is responsible for the exaggerated symptoms of HFD-induced obesity and associated dysregulation in glycemic homeostasis." (PMID 36145091, 2022). "It would also be interesting to know diets causing obesity had an impact on the regulatory elements of the genes for Jak3 and/or BCRP." (PMID 33814980, 2021). "In this report, we delineate the intestinal and brain functions of Jak3 and demonstrate how Jak3 deficiency not only affects obesity-associated gut dysbiosis but also the cognitive functions through microglial regulation of TREM2-medited activation and accumulation of Abeta and pTau in the brain." (PMID 36145091, 2022). "Since our data suggested the key role of Jak3 in both obesity-associated metabolic syndrome and gut dysbiosis, our natural next step was to see whether these mice with impaired Jak3 signaling had any cognitive functions impacted." (PMID 36145091, 2022). "Interestingly, while it was known that global Jak3 deficiency in general caused obesity-associated metabolic syndrome, the tissue-specific deficiency of Jak3 in metabolic-syndrome-associated cognitive impairment was not known." (PMID 36145091, 2022). "Moreover, obesity-associated decrease in colonic expression of Jak3 was observed in both male and female subjects compared with their normal counterparts." (PMID 33814980, 2021). "Mice with deficiency of Jak3 and Stat6 can display obesity and liver steatosis." (PMID 34506234, 2021).
Obesity (continued). "Baricitinib, a close chemical analog of ilunocitinib, exhibits significantly lower potency against JAK3, resulting in limited weight gain, thereby supporting its potential beneficial role in obesity and metabolic disease development." (PMID 40045302, 2025). "IEC-specific deficiency of Jak3 is responsible for cognitive impairment and exaggerated symptoms of cerebral cortex accumulation of Aβ and pTau during HFD-induced obesity." (PMID 36145091, 2022). "Overall, the molecular basis of compromised intestinal drug efflux during obesity indicated BCRP interactions with Jak3 was essential for BCRP tyrosine phosphorylation (BCRP-P) that facilitated BCRP-P interactions with β-catenin." (PMID 33814980, 2021). "Studies have shown that intestinal BCRP dysfunction in obesity results from reduced Janus kinase 3 (JAK3)-mediated phosphorylation, which is essential for BCRP localization and activity, leading to increased drug retention and dysregulated gut-liver communication." (PMID 40573999, 2025). "By increasing leptin levels, obesity alters adipose tissue macrophages’ (ATMs) metabolism through Janus kinase 3 (JAK3) and STAT3, and PI3K-Akt-mTOR pathways, increasing glycolytic enzymes’ activity and glucose uptake as well as inducing mitochondrial dysfunctions." (PMID 38558823, 2024). "Although obesity-associated metabolic syndrome comes with a cognitive impact, the intestinal mucosal specific role of Jak3 in such comorbidities was not known." (PMID 36145091, 2022). "Previously, we reported that obese humans have a reduced expression of intestinal Janus kinase-3 (Jak3), a non-receptor tyrosine kinase, and a deficiency of Jak3 in mice led to predisposition to obesity-associated metabolic syndrome." (PMID 36145091, 2022). "Results expressed the effects of weight gain appear to be caused by the loss of Jak3 which led to obesity and not an anomaly associated with familial transmission of microbiota from the other mice." (PMID 33814980, 2021). "However, the mechanisms through which Jak3 regulates the gut–brain axis and the associated cognitive functions during obesity are not known." (PMID 36145091, 2022). "In IEC, the essential roles of Jak3 include cytoskeletal remodeling, intestinal restitution, mucosal homeostasis, trans-molecular regulation of adapter protein Shc, and a deficiency of its functions leads to predisposition to chronic intestinal inflammation and systemic CLGI-associated obesity." (PMID 36145091, 2022). "Furthermore, PLAGL1 may be implicated in lipid metabolism and obesity through its effect on IDI1, PNPLA1, JAK3, and RAB37 expression." (PMID 30082726, 2018).
T cell lymphoma (9 papers, 2012 to 2025). "Our results indicate that inhibition of the JAK3/STAT5 pathway might be a promising strategy for treatment of EBV-associated T cell lymphoma." (PMID 27732937, 2016). "Furthermore, we found that EBV-infected γδ T cells of patients with EBV-associated T cell lymphoma showed activation of the JAK3/STAT5 pathway." (PMID 27732937, 2016). "66.7% of cases had mutations in genes of the JAK-STAT signaling pathway which was known as a major oncogenic mechanism in T cell lymphomas, including STAT5B mutations (4/9), JAK3 mutations (3/9), and STAT5A mutations (2/9)." (PMID 34895266, 2021). "A recent publication using integrated genomic sequencing shows gain-of-function mutations in JAK1, JAK3 and STAT5B in T cell prolymphocytic leukaemia (T-PLL), supporting the importance of JAK kinases for T cell lymphoma growth." (PMID 25820993, 2015). "Similar JAK3 inhibitors induce apoptosis in natural killer/T-cell lymphoma." (PMID 40565600, 2025). "In our patient, NGS analysis of 26-genes T-cell lymphoma panel found no pathogenic mutation and in particular no JAK3 deletion, but one cannot exclude genetic aberration(s) in other genes not tested in this panel." (PMID 32696224, 2021). "We examined the activation of the JAK3/STAT5 pathway in EBV-positive and -negative B, T and NK cell lines and in cell samples from patients with EBV-associated T cell lymphoma." (PMID 27732937, 2016).
cutaneous T cell lymphoma (8 papers, 2010 to 2023). "Constitutively activated tyrosine kinase JAK3 is implicated in the pathogenesis of cutaneous T-cell lymphomas (CTCL)." (PMID 37830594, 2023). "Deregulated JAK/STAT signaling due to JAK1 and JAK3 somatic mutations has been observed in Cutaneous T-Cell Lymphoma (CTCL)." (PMID 34055801, 2021). "Acquired mutations were recently described in cutaneous T-cell lymphomas for the JAK1, JAK3, STAT3, and STAT5B genes of the JAK-STAT pathway." (PMID 29262599, 2017). "JAK3 plays an important role in the pathogenesis of cutaneous T cell lymphoma." (PMID 33466582, 2021). "Inhibition of Jak3, STAT3 and STAT5 triggered overexpression of miR-22 and suppressed cancer proliferation in cutaneous T-Cell lymphoma." (PMID 28548950, 2017).
acute myeloid leukemia (7 papers, 2010 to 2025). Acute myeloid leukemia (AML) is a group of neoplasms arising from precursor cells committed to the myeloid cell-line differentiation. "Similar to the acute myeloid leukemia associated gain-of-function variant JAK3-A572V, expression of the JAK3-R840C variant enhanced the proliferation of transduced primary T cells and of cell lines in vitro." (PMID 29375547, 2017). "A recent study identified an activating allele of JAK3 (V674A) from an acute myeloid leukemia patient-derived retroviral cDNA library, and showed that JAK3V674A can transform the lymphoid pro-B-cell line BaF3 to IL-3-independent growth." (PMID 20149240, 2010). "Activating mutations of JAK3 are observed in 3.9%–10% of acute myeloid leukemia (AML) patients, but it is unclear whether AML cells are sensitive to JAK3 inhibitors, and no disease-related human AML cell model has been reported." (PMID 35111683, 2021). "Previous studies have shown that JAK3-inhibitor-VI is a promising candidate for treating acute myeloid leukemia." (PMID 37205181, 2023).
colitis (7 papers, 2017 to 2024). Inflammation of the colon. "As previously state, loss of Jak3 expression resulted in a predisposition to DSS-induced colitis, and untreated mice had a tendency to gain weight." (PMID 33814980, 2021). "We reported previously that Jak3 regulates intestinal inflammation and predisposition to colitis through interaction with and AJ localization of β-catenin." (PMID 28821617, 2017). "Colitis in Jak3 knockout mice is thought to be caused by a defect in the intestinal barrier." (PMID 33777833, 2021). "Jak3 plays an important role in such a scenario because Jak3 not only promotes expression of colonocyte differentiation markers in human IEC but loss of Jak3 expression in genetically modified mouse leads to compromised differentiation and predisposition of colitis." (PMID 33814980, 2021). "We showed that during DSS-induced colitis, Jak3-KO mice had shorter colon length, smaller cecum length, and shorter crypt heights compared to their littermate controls." (PMID 33814980, 2021). "A recent paper on JAK3 knockout mice and induced-colitis lends some support to this notion." (PMID 39507544, 2024). "In addition to the conventional role of Jaks in Jak-STAT pathways in immune cells, research from our laboratory, however, suggested that knocking out Jak3 gene in mice increases severity toward dextran sulfate sodium-induced colitis." (PMID 33814980, 2021). "The protein levels of JAK1, JAK3, and STAT5 were downregulated in mice with colitis after curcumin treatment, indicating that curcumin inhibited JAK-STAT signal activation." (PMID 33597887, 2020). "For example, mice in which differentiation of goblet cells is suppressed, such as those lacking Jak3 or overexpressing Claudin-1, are predisposed to spontaneous and DSS-induced colitis." (PMID 29596476, 2018). "Interestingly, although Jak3 interactions with the AJ protein β-catenin were essential for mucosal barrier functions and protection from colitis, the structural determinants and molecular mechanism of Jak3 interactions with β-catenin were not known." (PMID 28821617, 2017).
Hodgkins lymphoma (7 papers, 2010 to 2022). A heterogeneous group of malignant lymphoid neoplasms of B-cell origin characterized histologically by the presence of Hodgkin and Reed-Sternberg (HRS) cells in the vast majority of cases. "In Hodgkin lymphoma cells, inhibition of HSP90 led to loss of JAK1, JAK3, and Tyk2, and constitutive pY of STAT1, 3, 5, and 6 was ablated." (PMID 32272626, 2020). "SOCS1 inactivating mutations or deletions have been previously shown to abolish control of phospho-JAK2 or phospho-STAT5 signaling in primary mediastinal B-cell and Hodgkin lymphomas, recalling the picture described here for JAK3 and SOCS1." (PMID 27144517, 2016). "JAK1, JAK2, and JAK3 immunoprecipitates were prepared from the lysates of Hodgkin's lymphoma HDLM-2 or L540 cells, where persistently-active JAK1 and JAK2 or JAK3 are expressed, respectively." (PMID 20149240, 2010). "MS-1020 was shown to effectively block constitutively active JAK3 in the Hodgkin lymphoma cell lines, L540 and HLDM-2 and in the MDA-MB-468 breast cancer cell line." (PMID 27713312, 2010). "The novel JAK/STAT SMI, AUH-6-96 reduced p-STAT3 and its downstream target, SOCS3 in Hodgkin lymphoma L540 cells by blocking constitutively active JAK3." (PMID 27713312, 2010). "Hodgkin's lymphoma L540 cells had high levels of phospho-JAK3 but undetectable levels of phospho-JAK1 and -JAK2." (PMID 20149240, 2010).
melanoma (7 papers, 2011 to 2025). A malignant, usually aggressive tumor composed of atypical, neoplastic melanocytes. "In the same family (C11), a variant in JAK3 (JAK3V722I) did segregate with melanoma." (PMID 40072281, 2025). "While HFF-1 showed higher levels of EGFR (p = 0.001) and JAK-3 (p = 0.001) genes compared to MeWo, the melanoma cell line presented higher expression of ERBB2 (p = 0.001), and ITK (p = 0.04)." (PMID 38790974, 2024). "Interrogation of The Cancer Genome Atlas (TCGA) data showed that reduced expression of JAK3 is correlated with poorer prognosis in melanoma patients." (PMID 32051510, 2020). "Analysis of the CCLE dataset also unveiled the diminished mRNA level of JAK3 gene in metastatic melanoma cell lines over primary melanoma lines." (PMID 32051510, 2020). "Analysis of publicly available data also showed that elevated JAK3 expression is correlated with improved survival of melanoma patients." (PMID 32051510, 2020). "Reciprocal experiment showed that the overexpression of JAK3 in WM-266-4 metastatic melanoma cells suppressed their motility and invasion." (PMID 32051510, 2020). "Among these kinases, 6 (RPS6KB2, DSTYK, TBRG4, CDK4, POLR2E, FASTKD5) and 4 (STK26, PAK1, EPHB2 and JAK3) were consistently up- or down-regulated, respectively, in the metastatic lines of at least two pairs of melanoma cells." (PMID 32051510, 2020). "Around 300 kinases were detected in each pair of cell lines, and the results showed that Janus kinase 3 (JAK3) was with reduced expression in the metastatic lines of all three pairs of melanoma cells." (PMID 32051510, 2020). "Our results showed that reduced JAK3 expression is correlated with increased migration and invasion of cultured melanoma cells." (PMID 32051510, 2020). "We further demonstrated that JAK3 suppresses the migratory and invasive abilities of melanoma cells in vitro, which involves diminished enzymatic activities of secreted matrix metalloproteinases." (PMID 32051510, 2020). "In combination with TCGA data, we discovered that JAK3 plays important roles in melanoma progression." (PMID 32051510, 2020). "Reciprocally, ectopic overexpression of JAK3 in WM-266-4 metastatic melanoma cells led to diminished enzymatic activities of secreted MMP-2 &9." (PMID 32051510, 2020). "For instance, JAK3 displayed consistently lower levels of expression in all three metastatic lines of the paired melanoma cells." (PMID 32051510, 2020). "In summary, our targeted kinome profiling method provides a systematic assessment about kinome reprogramming during melanoma metastasis and our results provides important lines of evidence to support JAK3 as a potential suppressor for melanoma metastasis." (PMID 32051510, 2020). "Furthermore, we demonstrated that differential expression of all investigated Ibrutinib target genes (i.e., BTK, EGFR, ERBB2, ITK, JAK3, and TEC) is associated with apoptotic mechanisms in clinical melanoma samples." (PMID 38790974, 2024). "In addition, the activities of secreted MMPs are negatively correlated with the expression levels of JAK3 gene in primary and metastatic melanoma cells, illustrating that JAK3 modulates melanoma cell invasion by regulating the activity of secreted MMPs." (PMID 32051510, 2020). "Moreover, JAK3 suppresses the migration and invasion of cultured melanoma cells by modulating the activities of matrix metalloproteinases 2 and 9 (MMP-2 and MMP-9)." (PMID 32051510, 2020). "To address this, we first investigated whether JAK3 gene is expressed at different levels in metastatic and primary melanoma tissues by analyzing the data retrieved from the Gene Expression Omnibus (GEO) and CCLE datasets." (PMID 32051510, 2020). "Furthermore, the mRNA expression of JAK3 was reduced in the metastatic over primary tumor tissues of melanoma patients, and in metastatic over primary melanoma cell lines." (PMID 32051510, 2020).
melanoma (continued). "Additionally, metastatic human melanoma cells/tissues exhibited diminished levels of JAK3 mRNA relative to primary melanoma cells/tissues." (PMID 32051510, 2020). "Moreover, our results reveal a role of JAK3 as a potential suppressor for melanoma metastasis." (PMID 32051510, 2020). "Thus, our quantitative proteomic results, combined with TCGA data and other datasets, suggest that JAK3 may suppress melanoma metastasis." (PMID 32051510, 2020). "The roles of JAK3 in melanoma progression, however, remain unclear." (PMID 32051510, 2020). "Therefore, we further investigated JAK3’s roles in melanoma metastasis in vitro." (PMID 32051510, 2020). "Our results from transwell migration and invasion assay showed that the WM-115 primary melanoma cells exhibited a modest, yet statistically significant increase in migratory capacity, and a marked elevation in invasive ability upon siRNA-mediated knock-down of JAK3." (PMID 32051510, 2020). "Gene mutations are often involved in tumorigenesis, the clustered deletions were found in ABL1, NOTCH1, RET, STK11, GNA11, and JAK3 genes in CRC, melanoma, and non-small cell lung cancers." (PMID 32850446, 2020). "Among them, JAK3, MAP4K4 and CCNH were consistently down-regulated in the metastatic lines of all three pairs of melanoma cells." (PMID 32051510, 2020). "Deregulated JAK3 and RNase L pathways in LNCaP prostate cancer cells, defective STAT1 and STAT2 activation in fibrosarcoma and melanoma cells and down-regulated IFNAR in high grade bladder cancer have all been reported to disable the innate immune signaling." (PMID 22194884, 2011). "Therefore, JAK3 may function together with BRMS1 and EDAR to suppress the migration and invasion of melanoma cells." (PMID 32051510, 2020). "Thus, EMT does not appear to contribute to elevated invasive capacity of the WM-266-4 melanoma cells, and the JAK3-mediated suppression of invasive capacity of melanoma cells is not attributed to EMT inhibition." (PMID 32051510, 2020).
prostate carcinoma (7 papers, 2010 to 2024). A carcinoma that arises from epithelial cells of the prostate gland. "In order to summarize these and other findings, we contrasted three JAK3+ patients, all of whom had a history of prostate cancer with 50 prostate cancer patients from our database not known to be JAK3+." (PMID 39507544, 2024). "Many of the immune response related (e.g., IRF8, JAK3, PTGER4, RELB, IFITM3) and part of the lipid metabolism related genes (e.g., NR1H4, PPARGC1B, PLIN1, HSD17B14) were identified to be adaptive which addressed their significance for prostate cancer." (PMID 36809527, 2023).